METTL3 (methyltransferase 3, N6-adenosine-methyltransferase complex catalytic subunit)
Description:
The METTL3-METTL14 heterodimer forms a N6-methyltransferase complex that methylates adenosine residues at the N(6) position of some RNAs and regulates various processes such as the circadian clock, differentiation of embryonic and hematopoietic stem cells, cortical neurogenesis, response to DNA damage, differentiation of T-cells and primary miRNA processing. In the heterodimer formed with METTL14, METTL3 constitutes the catalytic core. N6-methyladenosine (m6A), which takes place at the 5'-[AG]GAC-3' consensus sites of some mRNAs, plays a role in mRNA stability, processing, translation efficiency and editing. M6A acts as a key regulator of mRNA stability: methylation is completed upon the release of mRNA into the nucleoplasm and promotes mRNA destabilization and degradation. In embryonic stem cells (ESCs), m6A methylation of mRNAs encoding key naive pluripotency-promoting transcripts results in transcript destabilization, promoting differentiation of ESCs (By similarity). M6A regulates the length of the circadian clock: acts as an early pace-setter in the circadian loop by putting mRNA production on a fast-track for facilitating nuclear processing, thereby providing an early point of control in setting the dynamics of the feedback loop (By similarity). M6A also regulates circadian regulation of hepatic lipid metabolism. M6A regulates spermatogonial differentiation and meiosis and is essential for male fertility and spermatogenesis (By similarity). Also required for oogenesis (By similarity). Involved in the response to DNA damage: in response to ultraviolet irradiation, METTL3 rapidly catalyzes the formation of m6A on poly(A) transcripts at DNA damage sites, leading to the recruitment of POLK to DNA damage sites. M6A is also required for T-cell homeostasis and differentiation: m6A methylation of transcripts of SOCS family members (SOCS1, SOCS3 and CISH) in naive T-cells promotes mRNA destabilization and degradation, promoting T-cell differentiation (By similarity). Inhibits the type I interferon response by mediating m6A methylation of IFNB. M6A also takes place in other RNA molecules, such as primary miRNA (pri-miRNAs). Mediates m6A methylation of Xist RNA, thereby participating in random X inactivation: m6A methylation of Xist leads to target YTHDC1 reader on Xist and promote transcription repression activity of Xist. M6A also regulates cortical neurogenesis: m6A methylation of transcripts related to transcription factors, neural stem cells, the cell cycle and neuronal differentiation during brain development promotes their destabilization and decay, promoting differentiation of radial glial cells (By similarity). METTL3 mediates methylation of pri-miRNAs, marking them for recognition and processing by DGCR8. Acts as a positive regulator of mRNA translation independently of the methyltransferase activity: promotes translation by interacting with the translation initiation machinery in the cytoplasm. Its overexpression in a number of cancer cells suggests that it may participate in cancer cell proliferation by promoting mRNA translation. During human coronavirus SARS-CoV-2 infection, adds m6A modifications in SARS-CoV-2 RNA leading to decreased RIGI binding and subsequently dampening the sensing and activation of innate immune responses.
Synonyms: hMETTL3; MT-A70; Spo8; M6A; IME4
Tractability: Small molecule: a structure with a bound ligand is known; a high-quality ligand is known. PROTAC: UniProt records ubiquitination sites on it; ubiquitination databases record sites on it; its protein half-life has been measured; a small molecule that binds it is known.
Target class: Enzyme; Transferase
Chemical probes: STM2457 (high quality)
Gene: Protein-coding gene on chromosome 14 (21,498,128 to 21,511,362, reverse strand). Ensembl gene ENSG00000165819.
Subcellular location: Nucleus; Nucleus speckle; Cytoplasm
Subcellular location (Human Protein Atlas): Cytosol; Nucleoplasm; Golgi apparatus; Nuclear bodies
Pathways (Reactome):
Metabolism of RNA: Processing of Capped Intron-Containing Pre-mRNA
Gene Ontology:
Molecular function: mRNA binding; mRNA m(6)A methyltransferase activity; mRNA N6-methyladenosine dioxygenase activity; protein binding; protein heterodimerization activity; RNA methyltransferase activity; S-adenosyl-L-methionine binding
Biological process: cellular response to UV; DNA damage response; dosage compensation by inactivation of X chromosome; mRNA modification; mRNA processing; mRNA splicing, via spliceosome; negative regulation of type I interferon-mediated signaling pathway; positive regulation of cap-independent translational initiation; positive regulation of translation; primary miRNA processing; RNA methylation; RNA stabilization; circadian rhythm; endothelial to hematopoietic transition; forebrain radial glial cell differentiation; gliogenesis; mRNA destabilization; negative regulation of Notch signaling pathway; oogenesis; regulation of hematopoietic stem cell differentiation; regulation of meiotic cell cycle; regulation of T cell differentiation; spermatogenesis; stem cell population maintenance; regulation of RNA stability
Cellular component: cytoplasm; cytosol; nuclear body; nuclear speck; nucleoplasm; nucleus; RNA N6-methyladenosine methyltransferase complex
Genetic constraint (gnomAD): Loss-of-function variants: 41 observed, 65.88 expected, observed/expected ratio (o/e) 0.62, 90% interval 0.48 to 0.81. The upper end of that interval is the gene's LOEUF score, 0.81, which puts it in group 3 of 6, group 1 being the genes least tolerant of losing a copy. Missense variants: 424 observed, 749.18 expected, observed/expected ratio (o/e) 0.57, 90% interval 0.52 to 0.61. Synonymous variants: 254 observed, 274.32 expected, observed/expected ratio (o/e) 0.93, 90% interval 0.83 to 1.03.
Homologues: Orthologues: chimpanzee METTL3 (100% identical), macaque METTL3 (99% identical), dog METTL3 (98% identical), pig METTL3 (98% identical), rabbit METTL3 (98% identical), mouse Mettl3 (97% identical), rat Mettl3 (97% identical), guinea pig METTL3 (93% identical), tropical clawed frog mettl3 (78% identical), zebrafish mettl3 (69% identical), Drosophila melanogaster Mettl3 (50% identical).
Diseases named in the same sentence as METTL3 in open-access papers:
METTL3 is named in the same sentence as 403 diseases in open-access papers, as found by Europe PMC text mining. Sharing a sentence is not in itself a finding about the gene and the disease. The quoted sentences say what the papers report.
gastric cancer (248 papers, 2019 to 2026). A primary or metastatic malignant neoplasm involving the stomach. "High expression of METTL3 in gastric cancer is associated with lymph node metastasis and advanced TNM stage." (PMID 38856795, 2024). "In 415 patients from The Cancer Genome Atlas (TCGA) cohort, METTL3 expression was increased in gastric cancer tissues and associated with poor patient prognosis." (PMID 38856795, 2024). "Here, this work showed that METTL3 is upregulated in gastric cancer tissues and is associated with poor prognosis." (PMID 38879589, 2024). "Recent studies have also uncovered the role of circular RNAs in promoting the progression of EBV-associated gastric carcinoma through the transactivation of METTL3." (PMID 39599775, 2024). "Our findings revealed that METTL3 is significantly overexpressed in gastric cancer and is closely linked to poor prognosis." (PMID 37822880, 2023). "In this study, our focus was on METTL3, a dysregulated gene observed in various cancers and known to be associated with gastric cancer development." (PMID 37822880, 2023). "In gastric cancer, higher expression of METTL3 is associated with poor prognosis, and mechanistically, METTL3 mediates the m6A modification of HDGF mRNA in a manner with IGF2BP3-dependent HDGF mRNA stability." (PMID 35541906, 2022). "In this study, we found that METTL3 is highly expressed in gastric cancer, and the high expression of METTL3 is associated with the poor prognosis of patients." (PMID 35742899, 2022). "As expected, this result produced a promising strategy to improve chemosensitivity and prognosis in gastric cancer by stimulating autophagy of ARHGAP5-AS1 or destabilizing ARHGAP5 caused by METTL3 removal." (PMID 35090469, 2022). "Reportedly, high expression of METTL3 is associated with poor prognosis of gastric cancer patients; METTL3 overexpression expedites epithelial–mesenchymal transition process and enhances the migrative and invasive abilities of gastric cancer cells." (PMID 35892080, 2022). "METTL3 is frequently associated with many types of cancers, such as gastric cancer, bladder cancer, and colorectal cancer." (PMID 35090469, 2022). "In gastric cancer, aberrant METTL3 expression is associated with poor prognosis of patients because of the m6A regulation of several key components (e.g., MCM5 and MCM6) in the MYC pathway." (PMID 34315512, 2021). "This study showed that METTL3 promoted the proliferation and metastasis of gastric cancer by modifying Yes-associated protein 1 (YAP1) mRNA m6A." (PMID 34394353, 2021). "The expression of METTL3 is increased in gastric cancer and associated with poor prognosis, indicating that the expression of METTL3 is an independent prognostic factor and effective predictor in gastric cancer." (PMID 32808488, 2020). "For example, METTL3 was reported to act as an oncogene associated with the tumor progression and metastasis in various cancers, such as gastric cancer, colorectal cancer, and pancreatic cancer." (PMID 32419773, 2020). "In contrast, low expression of METTL3 was significantly associated with poor survival in gastric cancer, liver cancer and pancreatic cancer." (PMID 32863943, 2020). "In this study, we investigated the underlying mechanism of METTL3 in human gastric cancer by focusing on the AKT signaling pathway." (PMID 30886897, 2019). "Furthermore, EBV-circRPMS1 has been shown to promote the progression of EBV-associated gastric cancer (EBVaGC) by recruiting Sam68 to the METTL3 promoter, inducing METTL3 expression." (PMID 40778336, 2025). "In gastric cancer patients, a high level of METTL3 was significantly associated with a low survival rate, and knockout of METTL3 could effectively inhibit the proliferation, migration, and invasion of gastric cancer cells." (PMID 38331776, 2024). "Studies have shown that acetylation of METTL3 is associated with the progression of gastric cancer." (PMID 39678510, 2024).
gastric cancer (continued). "In addition, fluctuations in m6A levels induced by METTL3 are closely associated with the malignant progression of tumors as well as the poor prognosis of patients with gastric cancer." (PMID 39678510, 2024). "METTL3 mostly causes GC progression and drug resistance in gastric cancer." (PMID 39678510, 2024). "In addition, a series of studies have presented that METTL3 is associated with the occurrence and lung metastasis of liver cancer, colorectal cancer, gastric cancer, bladder cancer, and glioblastoma." (PMID 36710350, 2023). "METTL3 has also been implicated in drug resistance in gastric cancer." (PMID 37822880, 2023). "Methyltransferase-like 3 (METTL3) modifying mRNA via N6-methyladenosine is involved in gastric cancer, whereby it upregulates Cyclin D1 levels and activates the Akt signaling pathway, as shown in loss-of-function experiments in gastric cancer cells." (PMID 36769170, 2023). "METTL3, classified as writers, inhibits SOX2 degradation for conducting the progression of colorectal carcinoma in an m6A-IGF2BP2–dependent manner and was linked with poor prognosis of gastric cancer due to METTL3-mediated HDGF of methylation facilitating cancer progression." (PMID 34295922, 2021). "For example, YTHDF1, YTHDF2, and especially METTL3 are associated with gastric cancer." (PMID 34277622, 2021). "Additionally, METTL3 was associated with elevated PD-L1 expression in gastric cancer cells." (PMID 38187373, 2023). "Furthermore, HBV infection is also associated with gastric cancer development, and a study showed that the hepatitis B X‐interacting protein could upregulate METTL3 during HBV infection." (PMID 35560957, 2023). "This article is aimed at exploring the relationship between the phosphatase 2A catalytic subunit Cα (PP2Acα, encoded by PPP2CA) and methyltransferase-like 3 (METTL3) in the malignant progression of gastric cancer (GC)." (PMID 34485508, 2021). "Studies primarily in colorectal and gastric cancer models have revealed a key oncogenic axis: METTL3 promotes Wnt/β-catenin signaling by recruiting YTHDF reader proteins to degrade APC mRNA." (PMID 41597255, 2026). "In gastric cancer stem cells, METTL3 modifies the 3’UTR of NDUFA4 (NADH dehydrogenase 1 alpha subcomplex 4) mRNA, recruits IGF2BP1 to increase NDUFA4 mRNA stability, and promotes oxidative metabolism." (PMID 41597255, 2026). "Gastric cancer is a highly prevalent disease worldwide, and Mettl3 has emerged as a key player in its pathogenesis." (PMID 41517663, 2026). "The gastric cancer organoid culture assay showed that after 5-FU treatment and overexpression of METTL3, the diameters of organoids were decreased significantly." (PMID 39744419, 2025). "Specifically, the activation of the tumor necrosis factor receptor-associated factor 6 (TRAF6)/NF-κB/fibroblast growth factor 18 (FGF18) pathway is required for gastric cancer cell proliferation through METTL3-mediated m6A methylation." (PMID 40986143, 2025). "In gastric cancer, global dysregulation of the m6A machinery has also been documented, with METTL3, FTO, YTHDFs, IGF2BPs and hnRNPA2B1 frequently upregulated in patient tissues and associated with poor prognosis, advanced stages and metastasis." (PMID 41228380, 2025). "In gastric cancer, METTL3-driven m6A methylation at specific adenosines on the long non-coding RNAs (lncRNAs) PSMA3-AS1 (A1225) and MIR22HG (A2041) is enriched in GCSCs compared with non-stem cells." (PMID 41228380, 2025). "For instance, METTL3 “writer” is upregulated in oxaliplatin-resistant gastric cancer cells and promotes resistance via the DNA repair pathway." (PMID 41228380, 2025). "For instance, in gastric cancer (GC), METTL3, a major RNA N6-adenosine methyltransferase, is upregulated." (PMID 40271153, 2025). "miR-1269b influences the cell proliferation, migration, and invasion of gastric cancer by regulating the expression of METTL3." (PMID 41229443, 2025).
gastric cancer (continued). "METTL3 can also promote oxaliplatin resistance of gastric cancer (GC) cells by promoting the stability of PARP1 mRNA." (PMID 41194259, 2025). "According to the existing literature, METTL3 has been shown to promote the growth and metastasis of gastric cancer cells." (PMID 40825934, 2025). "Functionally, METTL3, one of the best characterized m6A “writers”, appears to contribute to gastric cancer progression by stabilizing oncogenic transcripts and modulating key signaling pathways." (PMID 41228380, 2025). "By inhibiting METTL3, m6A marks on oncogenic mRNAs are reduced, destabilizing them and suppressing gastric cancer growth." (PMID 41228380, 2025). "METTL3 is crucial for epithelial-mesenchymal transition (EMT) and tumor metastasis, linking high METTL3 levels in gastric cancer cells to poor prognosis." (PMID 39791162, 2025). "METTL3 drives tumorigenesis and lung/lymph node metastasis in gastric cancer via the PBX1/GCH1 axis, elevating tetrahydrobiopterin levels to enhance metastatic aggressiveness." (PMID 40986143, 2025). "In gastric cancer, elevated expression levels of METTL3 were demonstrated to be an independent poor prognostic indicator." (PMID 40356909, 2025). "They found that METTL3 assumes a regulatory role in mitochondrial metabolism in gastric cancer cells." (PMID 39422510, 2024). "Dysregulation of METTL3 contributes to the oncogenesis of gastric cancer as METTL3 regulates the translation of oncogenes." (PMID 38856795, 2024). "In gastric cancer stem‐like cells, METTL3 upregulation is responsible for PARP1 overexpression which is associated with oxaliplatin resistance due to DNA damage repair." (PMID 39661414, 2024). "Helicobacter pylori infection increased the expression level of METTL3 in gastric cancer cells, thereby leading to the upregulation of STAT5A." (PMID 38879589, 2024). "For example, miR-4429, which targets METTL3 in gastric cancer, can inhibit the proliferation of GC cells and induce apoptosis." (PMID 39372415, 2024). "ARHGAP5-AS1 stimulates m6A modification of ARHGAP5 mRNA to stabilize it, by recruitment of the m6A writer METTL3 in the cytoplasm, and this event induces gastric cancer chemoresistance." (PMID 39280246, 2024). "METTL3 knockdown significantly inhibited the growth of gastric cancer(GC), and METTL3 acted as a methyltransferase to regulate the expression of genes related to the TGF-β/smad pathway, especially METTL3 modifies Smad3 mRNA through m6A." (PMID 39289775, 2024). "For example, in gastric cancer with METTL3 overexpression, METTL3 knockdown hinders cell proliferation and migration capacity." (PMID 38665783, 2024). "METTL3 is highly expressed in gastric cancer, promotes proliferation and migration of gastric cancer cells and correlates with poor prognosis of patients." (PMID 39289775, 2024). "For example, METTL3 is upregulated and promotes tumour progression in colorectal cancer, gastric cancer, and breast cancer." (PMID 39095708, 2024). "In gastric cancer, <5% of total METTL3-bound transcripts possess m6A sites, demonstrating that METTL3 preferentially binds to non-m6A methylated mRNAs." (PMID 38444581, 2024). "The results of previous studies indicate that the expression level of METTL3 is significantly elevated in gastric cancer tissues and cells." (PMID 39678510, 2024). "METTL3 was significantly elevated and promoted the proliferation of gastric cancer by regulating the expression of MYC pathway in the post-transcriptional modification." (PMID 39009956, 2024). "Knockdown of METTL3 significantly inhibited proliferation, migration, and progression of epithelial-mesenchymal transition in gastric cancer cells." (PMID 38856795, 2024). "Targeting METTL3 can improve the efficacy of immunotherapy, alleviate chemotherapy resistance, and inhibit tumor growth, which is an advantage of using METTL3 as a target for gastric cancer." (PMID 39678510, 2024).